PPOX (protoporphyrinogen oxidase)
Description:
Catalyzes the 6-electron oxidation of protoporphyrinogen-IX to form protoporphyrin-IX.
Synonyms: PPO; V290M; VP; VPCO
Tractability: Small molecule: a structure with a bound ligand is known; a high-quality ligand is known; it has a high-quality binding pocket; it belongs to a druggable protein family. Antibody: UniProt places it where antibodies can reach, with medium confidence. PROTAC: its protein half-life has been measured; a small molecule that binds it is known.
Target class: Enzyme; Oxidoreductase
Gene: Protein-coding gene on chromosome 1 (161,165,837 to 161,178,013, forward strand). Ensembl gene ENSG00000143224.
Subcellular location: Mitochondrion inner membrane
Subcellular location (Human Protein Atlas): Mitochondria; Cytosol; Vesicles
Pathways (Reactome):
Metabolism: Heme biosynthesis
Gene Ontology:
Molecular function: oxygen-dependent protoporphyrinogen oxidase activity; flavin adenine dinucleotide binding; oxidoreductase activity
Biological process: heme B biosynthetic process; heme biosynthetic process; porphyrin-containing compound biosynthetic process; heme A biosynthetic process; response to xenobiotic stimulus
Cellular component: mitochondrial membrane; mitochondrion; mitochondrial inner membrane; mitochondrial intermembrane space
Genetic constraint (gnomAD): Loss-of-function variants: 24 observed, 58.1 expected, observed/expected ratio (o/e) 0.41, 90% interval 0.3 to 0.58. The upper end of that interval is the gene's LOEUF score, 0.58, which puts it in group 2 of 6, group 1 being the genes least tolerant of losing a copy. Missense variants: 512 observed, 637.36 expected, observed/expected ratio (o/e) 0.8, 90% interval 0.75 to 0.86. Synonymous variants: 224 observed, 249.5 expected, observed/expected ratio (o/e) 0.9, 90% interval 0.8 to 1.
Gene-disease validity (ClinGen):
ClinGen rates the evidence that PPOX causes each of these diseases.
variegate porphyria (semidominant): Strong.
Homologues: Orthologues: chimpanzee PPOX (100% identical), macaque PPOX (99% identical), rabbit PPOX (93% identical), dog PPOX (90% identical), mouse Ppox (89% identical), guinea pig PPOX (88% identical), pig PPOX (88% identical), rat Ppox (88% identical), zebrafish ppox (52% identical), tropical clawed frog ppox (51% identical), Drosophila melanogaster Ppox (37% identical), Caenorhabditis elegans lsd-1 (14% identical), and 1 more. Paralogues in human: PAOX (17% identical), MAOB (16% identical), SMOX (16% identical), IL4I1 (15% identical), MAOA (14% identical), KDM1A (13% identical), KDM1B (13% identical).
Diseases named in the same sentence as PPOX in open-access papers:
PPOX is named in the same sentence as 33 diseases in open-access papers, as found by Europe PMC text mining. Sharing a sentence is not in itself a finding about the gene and the disease. The quoted sentences say what the papers report.
variegate porphyria (18 papers, 2008 to 2025). Variegate porphyria is a form of acute hepatic porphyria characterized by the occurrence of neuro-visceral attacks with or without the presence of cutaneous lesions. "In our two cases biochemistry revealed a porphyria and consecutive molecular genetic testing showed in each case a homozygous variant in the PPOX gene, which corresponds to a variegate porphyria." (PMID 40114189, 2025). "Variegate Porphyria (VP) is an inherited rare disorder that is caused by mutations in the protoporphyrinogen oxidase (PPOX) gene." (PMID 35164799, 2022). "Variegate porphyria (VP), one of the acute hepatic porphyrias, is caused by a protoporphyrinogen oxidase (PPOX) mutation." (PMID 36386813, 2022). "Variegate porphyria is a very rare and autosomal dominant disorder which is caused by the mutations in protoporphyrinogen oxidase." (PMID 35164799, 2022). "Variegate porphyria (VP) is one of a group of porphyrias caused by mutations in protoporphyrinogen oxidase (PPOX) gene." (PMID 35164799, 2022). "Variegate porphyria (VP) is caused by deficiency of protoporphyrinogen oxidase (PPOX) that causes accumulation of δ -aminolevulinic acid (ALA)." (PMID 33801069, 2021). "Variegate porphyria (VP) is an autosomal-dominant disease caused by mutation of the protoporphyrinogen oxidase gene (PPOX)." (PMID 32026031, 2018). "Variegate porphyria is due to a deficiency of protoporphyrinogen oxidase which leads to accumulation of protoporphyrins and coproporphyrins in the stool, as well as ALA and PBG in the urine." (PMID 25525547, 2014). "A partial deficiency in Protoporphyrinogen oxidase (PPOX) produces the mixed disorder Variegate Porphyria (VP), the second acute porphyria more frequent in Argentina." (PMID 18570668, 2008). "Variegate porphyria occurs due to a deficiency in protoporphyrinogen oxidase (PPOX)." (PMID 39409147, 2024). "In humans, disruptions in the heme biosynthetic pathway are associated with various types of porphyrias, including variegate porphyria that results from the decreased activity of protoporphyrinogen oxidase IX (PPO; E.C.1.3.3.4), the enzyme catalyzing the penultimate step of the heme biosynthesis." (PMID 36224252, 2022). "Variegate porphyria (VP), another autosomal dominant type of hepatic porphyria, is the result of decreased protoporphyrinogen oxidase (PPOX) activity, the next-to-last enzyme in haem biosynthesis, and is characterized by skin lesions and acute attacks." (PMID 27788171, 2016). "Variegate porphyria (VP, OMIM 176200) is an autosomal dominant disease caused by mutations in the protoporphyrinogen oxidase (PPOX) gene, causing a partial defect of the seventh catalytic step of the haem biosynthetic pathway." (PMID 23324528, 2013).
porphyria (8 papers, 2008 to 2025). Porphyria is a group of diseases in which substances called porphyrins build up, negatively affecting the skin or nervous system. "The WES result reported a novel homozygous pathogenic variant (c.1072G > A p.G358R) in PPOX gene which indicates the Porphyria Variegate." (PMID 35164799, 2022). "Our studies reveal that CLPX mutations may cause anemia and porphyria via dysregulation of ALAS, FECH, and PPOX activities, as well as of iron metabolism." (PMID 34280433, 2021). "At the Royal Prince Alfred Hospital in Australia, a cohort of 36 porphyria patients of European descent and their family members were evaluated for clinical history, biochemical profile and detection of pathogenic mutations in haem biosynthetic pathway genes (HMBS, CPOX, PPOX or FECH)." (PMID 27507172, 2016).
acute porphyria (4 papers, 2008 to 2023). "We describe here two partial deletions within the PPOX gene, indicating that partial gene deletions should be considered in the genetic diagnosis of all acute porphyrias." (PMID 23324528, 2013).
anemia (4 papers, 2014 to 2025). A reduction in the number of red blood cells, the amount of hemoglobin, and/or the volume of packed red blood cells. "Furthermore, in the Cellular Processes pathways, the polysaccharide synthetic enzyme gene (pelG) was depleted in the IDA group, while protoporphyrin biosynthesis genes (PPOX and hemY) were elevated in the Non-Anemia group." (PMID 39065088, 2024).
glioma (4 papers, 2020 to 2025). A benign or malignant brain and spinal cord tumor that arises from glial cells (astrocytes, oligodendrocytes, ependymal cells). "Interestingly, however, in only three genes mRNA expression (HMBS, UROD and PPOX) was altered in the direction expected to result in increased PpIX concentrations in WHO grade IV gliomas, whereas the remaining 5 up-/downregulations were actually observed in the respective opposite directions." (PMID 32722247, 2020). "According to our data, we found distinct increases in the 5-ALA metabolizing enzymes CPOX, PPOX, and FECH and decreases in the PpIX exporting transporter ABCG2 on protein level in fluorescing glioma samples." (PMID 35665365, 2022). "In this sense, we recently observed significant differences in the mRNA expression in 8 of 11 analyzed genes (HMBS, UROD, FECH, PPOX, SLC15A2, ALAD, UROS, and ABCB6) involved in the heme biosynthesis between WHO grade II and IV gliomas." (PMID 33562253, 2021). "Significant differences in mRNA expression included increases of HMBS, UROD, FECH and PPOX as well as decreases of SLC15A2, ALAD, UROS and ABCB6 in WHO IV gliomas." (PMID 32722247, 2020). "The authors also reported that each of the assessed enzymes showed increased expression in the glioma stem-like cell-enriched model, specifically PEPT2, ABCB6, 5-aminolevulinate dehydratase (5-ALAD), and protoporphyrinogen oxidase (PPOX), with a fourfold increase." (PMID 41157189, 2025). "The results of this study demonstrate that protein levels of the investigated heme biosynthesis factors do not correlate with mRNA expression in gliomas in most cases (CPOX, PPOX, and FECH)." (PMID 35665365, 2022). "To this end, we compared the mRNA as well as protein expression levels of CPOX, PPOX, FECH and ABCG2 in glioma tissue samples with presence of strong 5-ALA induced fluorescence during surgery to non-fluorescing glioma samples." (PMID 35665365, 2022).
acute intermittent porphyria (3 papers, 2018 to 2024). Acute intermittent porphyria is the most frequent and the most severe form of the acute hepatic porphyrias. "Acute intermittent porphyria (AIP), HCP, and VP are inherited in an autosomal dominant way and result from a deficiency of one of the enzymes, hydroxymethylbilane synthase (HMBS), coproporphyrinogen oxidase (CPOX), and protoporphyrinogen oxidase (PPOX), respectively." (PMID 29553924, 2018).
cholangitis (1 paper, 2026). An acute or chronic inflammatory process affecting the biliary tract. "In this remarkable case hepatic heme synthesis was induced in the transplanted liver through medication (metamizole), stress and infection (cholangitis), unmasking previously undiscovered partial enzyme deficiency of PPOX." (PMID 41841034, 2026).
liver disease (1 paper, 2023). "Whereas phenotypes of the index patients with mutated PKHD1, TMEM67, and PPOX corresponded with those elsewhere reported, how F11R variation underlies liver disease remains unclear." (PMID 37471416, 2023).
Myelodysplasia (1 paper, 2018). Clonal hematopoietic stem cell disorders characterized by dysplasia (ineffective production) in one or more hematopoietic cell lineages, leading to anemia and cytopenia. "Taken together, the splicing alterations in ABCB7 and PPOX were the candidates that might be responsible for ring sideroblast formation in SF3B1-mutated myelodysplasia." (PMID 30194306, 2018).
vulvar cancer (1 paper, 2022). "In our studies, the resistance to PDT in vulvar cancer cell lines developed as a result of changes in the amount of heme metabolism enzymes (PPOX, FECH) that led to decreased amount of PpIX, changes in the number of mitochondria and cellular metabolism, as well as ROS and antioxidant capacity." (PMID 36499013, 2022).
cancer (3 papers, 2013 to 2022). A tumor composed of atypical neoplastic, often pleomorphic cells that invade other tissues. "For the non-cancer HFFF2 cells, a decrease in the level of all mRNA tested, FECH but also PPOX and ABCG2, was indeed observed following combination of all treatments." (PMID 35886979, 2022).
tumor (3 papers, 2020 to 2022). "PPOX might act as a tumor suppressor and play a crucial role in the development of HCC." (PMID 32899915, 2020). "Both PPOX and HMBS play key roles as tumor suppressors in the hepatocarcinogenesis." (PMID 36147508, 2022).
metabolic disease (2 papers, 2024 to 2025). A congenital disorder (due to inherited enzyme abnormality) or acquired (due to failure of a metabolically important organ) disorder resulting from an abnormal metabolic process. "VP is a metabolic disease due to pathogenic variants in the protoporphyrinogen oxidase (PPOX) gene which leads to a strongly decreased activity of protoporphyrinogen oxidase, the penultimate enzyme in the hembiosynthesis pathway." (PMID 40114189, 2025).
genetic disorders (1 paper, 2017). "WES enabled timely diagnosing of genetic diseases, validation of causality of specific genetic disorders of PTPN23, KCTD3, SCN3A, PPOX, FRMPD4, and SCN1B, and setting dual diagnoses by detecting two causative variants in distinct genes in the same patient." (PMID 27848944, 2017).
PPOX also shares sentences with these, for which no sentence is quoted: infection (11 papers); fungal infection (6); hereditary coproporphyria (5); Acute hepatic porphyria (3); asthma (1); autosomal dominant disease (1); blood disorders (1); deafness (1); endometrial carcinoma (1); gastric cancer (1); hereditary spastic paraplegia (1); hypoglycaemia (1); immune deficiency (1); malaria (1); male infertility (1); progressive external ophthalmoplegia (1); Respiratory insufficiency (1); signet ring cell carcinoma (1); viral infection (1).